CXCR3 (C-X-C motif chemokine receptor 3)
Description:
[Isoform 1]: Receptor for the C-X-C chemokines CXCL9, CXCL10 and CXCL11, and mediates the proliferation, survival and angiogenic activity of human mesangial cells (HMC) through a heterotrimeric G-protein signaling pathway. Probably promotes cell chemotaxis response. Upon activation by PF4, induces activated T-lymphocyte migration mediated via downstream Ras/extracellular signal-regulated kinase (ERK) signaling. [Isoform 2]: Receptor for the C-X-C chemokine CXCL4 and also mediates the inhibitory activities of CXCL9, CXCL10 and CXCL11 on the proliferation, survival and angiogenic activity of human microvascular endothelial cells (HMVEC) through a cAMP-mediated signaling pathway. Does not promote cell chemotaxis response. Interaction with CXCL4 or CXCL10 leads to activation of the p38MAPK pathway and contributes to inhibition of angiogenesis. Overexpression in renal cancer cells down-regulates expression of the anti-apoptotic protein HMOX1 and promotes apoptosis. [Isoform 3]: Mediates the activity of CXCL11.
Synonyms: CD183; GPR9; CKR-L2; CMKAR3; IP10-R; MigR; CD182; Mig-R
Tractability: Small molecule: a structure with a bound ligand is known; a high-quality ligand is known; it belongs to a druggable protein family. Antibody: UniProt places it where antibodies can reach, with high confidence; its Gene Ontology location is reachable by antibodies, with high confidence; UniProt predicts a signal peptide or a membrane-spanning region. PROTAC: a small molecule that binds it is known.
Target class: Peptide receptor (family A GPCR); Membrane receptor; Family A G protein-coupled receptor; CXC chemokine receptor; Chemokine receptor
Gene: Protein-coding gene on chromosome X (71,615,916 to 71,618,511, reverse strand). Ensembl gene ENSG00000186810.
Subcellular location: Cell membrane (Isoform 1); Cell membrane (Isoform 2)
Pathways (Reactome):
Signal Transduction: Chemokine receptors bind chemokines; G alpha (i) signalling events
Developmental Biology: Differentiation of naive CD4+ T cells to T helper 1 cells (Th1 cells)
Gene Ontology:
Molecular function: C-C chemokine receptor activity; chemokine binding; protein binding; C-C chemokine binding; chemokine receptor activity; C-X-C chemokine receptor activity; G protein-coupled receptor activity
Biological process: cell surface receptor signaling pathway; regulation of cell adhesion; calcium-mediated signaling; cell adhesion; cell chemotaxis; chemotaxis; immune response; positive regulation of cytosolic calcium ion concentration; chemokine-mediated signaling pathway; G protein-coupled receptor signaling pathway; inflammatory response; regulation of leukocyte migration; T cell chemotaxis
Cellular component: cell surface; cytoplasm; external side of plasma membrane; plasma membrane; membrane
Homologues: Orthologues: chimpanzee CXCR3 (100% identical), macaque CXCR3 (99% identical), rabbit CXCR3 (89% identical), dog CXCR3 (89% identical), pig CXCR3 (88% identical), mouse Cxcr3 (86% identical), guinea pig CXCR3 (85% identical), rat Cxcr3 (85% identical), tropical clawed frog cxcr3 (45% identical), zebrafish cxcr3.1 (41% identical), zebrafish cxcr3.3 (32% identical). Paralogues in human: CXCR2 (38% identical), CXCR5 (37% identical), CXCR1 (35% identical), CCR10 (35% identical), CXCR4 (33% identical), CCR6 (32% identical), CCR7 (32% identical), ACKR2 (31% identical), CCR1 (30% identical), CCR4 (30% identical), CCR5 (30% identical), CCR2 (29% identical), and 11 more.
Diseases named in the same sentence as CXCR3 in open-access papers:
CXCR3 is named in the same sentence as 460 diseases in open-access papers, as found by Europe PMC text mining. Sharing a sentence is not in itself a finding about the gene and the disease. The quoted sentences say what the papers report.
melanoma (132 papers, 2009 to 2025). A malignant, usually aggressive tumor composed of atypical, neoplastic melanocytes. "CXCR3-positive tumor cells are strongly associated with immune reactivity in tumors with thickness greater than 1 mm or with invasive, lethal melanoma." (PMID 40786052, 2025). "In particular, overexpression of CXCL10 and CXCR3 has been associated with advanced human cancers, including malignant melanoma." (PMID 39268223, 2024). "CXCR3 has been identified in numerous malignant cell lines and is linked to the prognosis of individuals with melanoma, colon cancer, and breast cancers." (PMID 38275412, 2024). "To validate that Mi-2β-regulated immune response is based on the enhanced IFNγ-signaling, we detected CXCR3 in the TME of Mi-2β-deficient melanomas by IHC with a specific anti-CXCR3 antibody." (PMID 38461299, 2024). "In cancer settings, it was also demonstrated that pre-cDC1, lineage-committed progenitors that give rise to cDC1, express the T helper type 1-associated chemokine receptor CXCR3 for homing functions to the melanoma." (PMID 36685500, 2022). "There are also studies associating the CXCL10/CXCR3 gene expression pathway with enhanced metastatic potential and poor prognosis in patients with melanoma and colon cancer." (PMID 35296026, 2022). "Among them, high CXCR3 expression in melanoma, colon, and breast cancers is associated with more malignant and aggressive tumors." (PMID 36479091, 2022). "CXCR3 expression on antigen-experienced peripheral CD8+ T cells has been associated with prolonged survival in patients with stage III melanoma, and CCR4 was highly co-expressed with CXCR3." (PMID 34454518, 2021). "RT-qPCR assays demonstrated that Ccl2/Ccr2 and Cxcl9/Cxcl10/Cxcr3 levels were higher in B16 melanoma tumors from Cbx3/HP1γ-deficient mice than those from controls." (PMID 34721405, 2021). "An increased CXCL10 and its corresponding receptor, CXCR3, are positively associated with malignant melanoma, ovarian carcinoma, multiple myeloma, B-cell lymphoma, and basal cell carcinoma." (PMID 34683090, 2021). "It has been shown in vivo that CXCR3-deficient NK cells cannot migrate to CXCL10-positive B16 melanoma tumor cells." (PMID 34768814, 2021). "According to the literature, CXCR3+CD8+ T cells have been identified as a biomarker that is associated with survival in melanoma patients with stage III disease, suggesting a potential role of this marker in SARS-CoV-2–infected patient survival." (PMID 34283810, 2021). "In a mouse model of melanoma, CXCR3 deficiency attenuates the infiltration of CD8+ T cells into tumours and thereby reduces antitumour immunity." (PMID 32439888, 2020). "Previously, CXCR3 expression in activated CD8+ T cells was reported to be associated with enhanced survival in melanoma patients with stage III disease." (PMID 32439888, 2020). "In mice CXCR3 deficiency led to faster growth of B16 melanoma, while loss of CXCR3 on circulating T cells from patients with melanoma was associated with metastases." (PMID 30899263, 2019). "T cell trafficking was further examined with CCR6 (MIP-3α receptor) and CXCR3 (IP-10/MIG/ITAC receptor) associated with intratumoral trafficking in melanoma." (PMID 31014399, 2019). "Nonetheless, high CXCR3 expression evaluated on 40 primary melanoma tumors tended to be associated with poor disease-free and overall survivals." (PMID 30420855, 2018). "In contrast, tyrosinase expression and surface metastases were significantly (p < 0.01 and 0.001, respectively) reduced in CXCR3-deficient mice, demonstrating that host cell expression of CXCR3 impacts melanoma engraftment or maintenance in the lungs." (PMID 28358049, 2017). "Increased tumor Cxcr3 expression has been linked to increased incidence of metastasis and poorer patient prognosis in several cancer types, including melanoma, especially those cases expressing WT-BRAF." (PMID 29050279, 2017).
melanoma (continued). "Increased expression of IP-10 and its receptor CXCR3 have also been associated with several advanced human cancers, including ovarian cancer, malignant melanoma, mutliple myeloma and basal cell carcinoma." (PMID 24884871, 2014). "For example, in melanoma samples, IP-10 expression was associated with the number of CXCR3+ lymphocytes and correlated with spontaneous regression of melanoma lesions." (PMID 25415223, 2014). "Consistently, CXCR3 was upregulated in the TME of Mi-2β-deficient melanomas." (PMID 38461299, 2024). "However, high CXCR3 expression in melanoma, colon, and breast cancers has been associated with more malignant and aggressive tumors." (PMID 39596815, 2024). "According to the literature, an increase in CXCR3+CD8+ T cells has been identified as a biomarker that is associated with survival in melanoma patients with stage III disease, suggesting a potential role of this marker in the survival of patients infected with SARS-CoV-2." (PMID 34283810, 2021). "Of major relevance, spontaneous regression of melanoma and other melanocytic lesions were associated with activation of endogenous type I interferons and infiltration by plasmacytoid dendritic cells and CXCR3+ cytotoxic T cells, these last recruited by elevation of CXCL10." (PMID 29064427, 2017). "Moreover, Cxcr3 expression is upregulated 12-fold in the more metastatic F10 variant of B16 melanoma cells compared to the poorly metastatic F1 variant." (PMID 29050279, 2017). "High CXCR3 expression in human VGP melanoma correlates with increased metastasis and poor patient outcomes, suggesting that CXCR3 signaling may be associated with the RGP to VGP transition." (PMID 25798946, 2015). "The loss of CXCR3 expression reduces lymph node metastasis in a murine melanoma model." (PMID 25254213, 2014). "Loss of CXCR3 expression in mouse B16F10 melanoma decreases metastasis to the lymph nodes by ~15%, suggesting that CXCR3 may play a role in lymph node metastasis." (PMID 24259307, 2013). "CXCR3 is upregulated in many primary and metastatic tumors, including prostate, breast, colorectal, lung, ovarian, kidney, melanoma, and multiple myeloma." (PMID 40786052, 2025). "DPP4 (CD26) inhibition elevates CXCR3 ligands, enhances CXCR3+ NK/T cell infiltration, and improves responses in melanoma, glioblastoma, and colorectal cancers." (PMID 40361472, 2025). "A study of 43 melanoma patients receiving pembrolizumab therapy found a significant increase in the percentage of CXCR3+ T cells in the blood following the first infusion." (PMID 39273452, 2024). "CXCR3, which has been investigated in various cancers, including colorectal cancer, melanoma, and renal cell carcinoma, directs the migration of immune cells to the tumor site and has been associated with prognosis." (PMID 39559348, 2024). "Certain chemokines, including CCR10 and CXCR3, have been demonstrated to play a pivotal role in the proliferation and metastasis of melanoma cells." (PMID 39079132, 2024). "Analyses of The Cancer Genome Atlas (TCGA) data sets showed that high tumor expression of CXCR3 correlated with better survival of melanoma patients with a hazard ratio of 0.59." (PMID 37045833, 2023). "In patients with melanoma or colorectal carcinoma, the recruitment of immune cells through CXCR3/CCR5 ligands is critical for the immune-mediated rejection of tumors." (PMID 36968220, 2023). "Upon upregulation of CXCL10, an inflammatory chemokine derived from astrocytes related to metastases, encephalophilic melanoma cells can correspondingly elevate the receptor CXCR3." (PMID 38104104, 2023). "CXCL10 chemokine secreted by astrocytes has been shown to elevate the receptor CXCR3 expression in tumor cells, thereby boosting absorption and migration capacity of melanoma BM cells." (PMID 38104104, 2023). "Recent studies have demonstrated the dual pro-/antitumor of CXCR3 in various cancers, including in melanoma, breast cancer, and renal cell carcinoma." (PMID 38104126, 2023).
melanoma (continued). "Of interest, addition of an anti-CXCR3 antibody after ACT in IL-2 NOG mice bearing the Me275 melanoma tumor, known to express CXCR3 ligands i.e. CXCL9/10/1140, with DMβ-transduced T cells significantly impaired tumor control." (PMID 37280206, 2023). "An in vitro study previously indicated that CXCR3 is expressed in a highly metastatic melanoma cell line (B16 F10) as well as a low metastatic melanoma cell line (B16 F1)." (PMID 37170733, 2023). "CD8+ T cells recruitment through CXCR3 signaling have also been reported in melanoma and other solid tumors." (PMID 35954489, 2022). "CXCR3 is another marker of dNK and expressed in tumor infiltrating -NK cells of colorectal cancer, breast cancer, melanoma, and glioblastoma." (PMID 36479091, 2022). "CXCL9 and CCL5 activated immune responses and enhanced ICB therapy in mouse model of ovary cancer, and the melanoma in CXCR3 knock-out mice exhibited decreased immune infiltration and poor prognosis." (PMID 35692828, 2022). "CXCR3 has been detected in many malignant cell lines and is correlated with the prognosis of patients with melanoma, colon cancer, and breast cancers." (PMID 36479091, 2022). "The subcutaneous injection of lethal or sub-lethal doses of melanoma B16 cells into CXCR3-/-mice establish a critical role for CXCR3 as a receptor for CXCL9, CXCL10, and CXCL11 during CTL migration." (PMID 35493527, 2022). "In a similar study using an in vivo xenograft model, it was demonstrated that activated CXCR3-positive human NK cells selectively migrate towards CXCL10-positive human melanoma tumor cells." (PMID 34768814, 2021). "Several studies examining the B16 tumour model in CXCR3−/− mice have indicated the importance of CXCR3 for CTL migration to the tumour site in melanoma." (PMID 33809369, 2021). "CXCL9 promotes the metastasis of melanoma cells through its combination with CXCR3 to enhance the permeability of tumor blood vessels." (PMID 33767987, 2021). "In a xenograft-harboring mouse model of CXCL10-transfected melanoma, overexpression of CXCR3 on NK cells after ex vivo growth with irradiated EBV-LCL feeder cells and IL-2 resulted in better trafficking and antitumor activity." (PMID 34970253, 2021). "The signaling via CXCR3 also results in a significant increase inIL-8 expression in BRAF wild type melanomas and these two events have been also associated with melanoma progression." (PMID 35011682, 2021). "CXCR3 is not only essential for T-cell trafficking to melanoma but can improve NK-cell infiltration of CXCL10-producing tumours." (PMID 34830780, 2021). "The CXCR3 knockout syngeneic murine model of B16 melanoma showed significantly accelerated tumor growth and reduced survival, along with reduced infiltration of CD8+ T cells into tumors." (PMID 34944392, 2021). "The CXCR3 marker was expressed in melanoma, breast cancer and glioma, whereas CXCR4 was present in lung cancer and CRC." (PMID 34209508, 2021). "For example, in a melanoma mouse model, CXCR3 was shown to be necessary for extravasation of CD8+ T cells to the tumor." (PMID 34440489, 2021). "Clinical data analysis showed that CXCR3 had elevated expression in melanoma, colon, ovarian and basal cell carcinoma 27-33." (PMID 34345201, 2021). "Expression of CXCR3 was necessary for CD8+ T-cell anti-tumor responses after treatment with PD-1 inhibitors in mouse models of melanoma." (PMID 34203869, 2021). "High levels of CXCL9 and CXCL10 expression in lymph nodes can promote melanoma cell metastasis through the CXCR3 signaling." (PMID 33407095, 2021). "Preclinical studies have shown that CXCR3 expression on melanoma cells increases metastasis to lymph nodes, and that inhibition of CXCR3 by antisense RNA decreased lymph node metastasis." (PMID 34207884, 2021). "One report mentions the infiltration of pre-cDC1 cells, a specific subset of bone marrow-derived conventional DC progenitors, important in the anti-cancer response, that home to B16F10 melanoma tumors using CXCR3." (PMID 34503058, 2021).
melanoma (continued). "According to transcriptome analysis in the TCGA database, the net effect of high CXCR3 expression in melanoma biopsies predicted favorable outcome in terms of overall survival." (PMID 32002296, 2020). "Particularly, CXCL9 and CXCL10 expression in the lymph nodes is reported to promote CXCR3-mediated metastasis of melanoma cells." (PMID 33195424, 2020). "C-X-C Motif Chemokine Receptor 3 (CXCR3) is one of the main receptors that is activated in tumor infiltrating lymphocytes (TILs) in melanoma, colorectal cancer and breast cancer." (PMID 32867162, 2020). "Some chemokines, such as CCR10 and CXCR3, have been shown to play an important role in the proliferation and metastasis of melanoma cells." (PMID 32310824, 2020). "Functional studies revealed that blockade of CXCL9 and CXCL10, or their receptor CXCR3, impairs recruitment of adoptively transferred T cells into melanoma tumors." (PMID 30873179, 2019). "Associated with thick primary lesions, the absence of lymphocytic infiltration and the presence of distant metastases—Increase in cell adhesion, migration, and invasion of CXCR3 expressing melanoma cells lines upon stimulation." (PMID 30420855, 2018). "Melanoma represents one situation in which metastasis moves cancer cells away from the skin but we must also consider a role of CXCR3 in attracting cancer cells to the skin." (PMID 30320116, 2018). "High expression of CXCR3, on melanoma infiltrating T cells together with the recruitment of effector memory CD8+ T cells has been associated with a better patient outcome." (PMID 30420855, 2018). "While CXCR3 expression on infiltrating immune cells generally restrains the melanoma, the expression of this receptor on melanoma cells themselves can lead to metastasis." (PMID 30320116, 2018). "Analysis of clinical data sets shows that co-expression of CXCR3 and its ligand CXCL10 is associated with early metastatic progression and increased metastatic potential in melanoma, colon carcinoma and renal cell carcinoma." (PMID 30177620, 2018). "Tumor growth was accelerated in CXCR3−/− melanoma-bearing mice and T cell infiltration was severly impaired." (PMID 30319622, 2018). "While CXCR3 expression was also detected in many cancers, such as breast cancer, malignant melanoma, renal cancer and colon cancer." (PMID 29690901, 2018). "Enhanced effector T cell recruitment via the CXCR3 axis has also been confirmed in the case of gastric cancer and melanoma." (PMID 30319622, 2018). "Accumulating evidence indicates that CXCR3 is expressed in various cancer types, including breast cancer, ovarian carcinoma, glioma and melanoma." (PMID 30177620, 2018). "Together, these studies highlight that the expression of CXCR3 on the surface of T cells is finely regulated and is essential to melanoma infiltration and tumor control." (PMID 30420855, 2018). "In contrast, CXCR3+ NK cells infiltrated tumor tissue in murine lymphoma and melanoma models in a CXCL10-dependent manner." (PMID 30319622, 2018). "Study of CXCR3 within this group of cancers has mainly focused on melanoma where several lines of evidence suggest that expression of CXCR3 on infiltrating T cells is associated with improved prognosis." (PMID 30320116, 2018). "Immunohistochemical study of primary human melanomas showed that upregulation of CXCL10 protein via type 1 interferons and the presence of CXCR3 infiltrating T cells was associated with spontaneous tumor regression." (PMID 30320116, 2018). "Consistent with this, melanomas with low expression of ligands for chemokine receptors CXCR3 and CCR5 are poorly infiltrated." (PMID 30126117, 2018). "Our findings are in good accordance with earlier results on CXCR3 and its ligands obtained in animal models, demonstrating anti-metastatic effects for colon cancer or melanoma." (PMID 29163806, 2017).